ENSG00000272617 (novel protein, COG8-PDF readthrough)
Gene: Protein-coding gene on chromosome 16 (69,328,644 to 69,334,871, reverse strand). Ensembl gene ENSG00000272617.
Genetic constraint (gnomAD): Loss-of-function variants: 13 observed, 13.67 expected, observed/expected ratio (o/e) 0.95, 90% interval 0.62 to 1.51. Missense variants: 210 observed, 223.3 expected, observed/expected ratio (o/e) 0.94, 90% interval 0.84 to 1.05. Synonymous variants: 98 observed, 89.29 expected, observed/expected ratio (o/e) 1.1, 90% interval 0.93 to 1.3.